NAMPT (nicotinamide phosphoribosyltransferase)
Diseases named in the same sentence as NAMPT in open-access papers (continued):
Sharing a sentence is not in itself a finding about the gene and the disease.
cancer (continued). "In addition, there was a differential effect noted between the induction of ROS in cancer cells compared to normal cells treated with NAMPT inhibitors, suggesting the existence of a therapeutic window for ROS induction with these agents." (PMID 32010616, 2019). "NAMPT is an attractive metabolic target for cancer treatment." (PMID 30856230, 2019). "In addition, NAMPT is capable of inducing cancer stemness and an invasive and drug-resistant phenotype." (PMID 31354474, 2019). "Despite promising preclinical data using NAMPT inhibitors in cancer models, early NAMPT inhibitors showed limited efficacy in several early phase clinical trials, necessitating the identification of strategies, such as drug combinations, to enhance their efficacy." (PMID 32010616, 2019). "ERCC1 deficiency is also associated with mitochondrial defects, suggesting that additional factors may contribute to NAMPT inhibitor sensitivity in this cancer subtype." (PMID 32010616, 2019). "Specifically, we determined whether cancer cells with an acquired resistance to NAMPT inhibition were also more sensitive to Gln depletion than parental cells." (PMID 29541451, 2018). "Therefore, NAMPT has been proposed as a viable cancer drug target, and many molecular agents have been developed that inhibit its enzymatic function, such as FK866, GNE618, and CHS-828." (PMID 29541451, 2018). "Our study identifies novel mechanisms of resistance to NAMPT inhibition, which may be useful to design more rational strategies for targeting cancer metabolism." (PMID 29541451, 2018). "NAMPT blockade also had beneficial effects in an acute lung injury model and may modify the cancer microenvironment through their anti-inflammatory properties." (PMID 28837586, 2017). "Therefore, we tested the ability of cells with different levels of NAMPT expression to form tumorspheres, a surrogate assay for the cancer stem-like phenotype." (PMID 29245920, 2017). "The protein ‘nicotinamide phosphoribosyltransferase’, which plays a fundamental role in providing an energy source for cancer cells through the biosynthesis of NAD+, was also among the identified proteins found to be significantly up regulated in the androgen independent cell lines." (PMID 28086232, 2017). "This could explain why, in clinical trials of cancer treatment, oral administration of FK866 or CHS828,20, 21 which inhibits NAMPT enzymatic activity, caused unwanted side effects dominated by gastrointestinal symptoms." (PMID 28333140, 2017). "NAD synthesis from Nam is catalyzed by nicotinamide phosphoribosyltransferase (NAMPT), which is the first and rate-limiting enzyme of this pathway, and has been associated with several diseases, including inflammation, metabolic disorders and cancer." (PMID 26675378, 2016). "More importantly, NAMPT has a crucial role in cancer cell metabolism." (PMID 28097126, 2016). "Finally, NAMPT has an anti-apoptotic activity in many cancers, and we have recently found its overexpression in thyroid malignancies." (PMID 26767650, 2016). "Our results indicate that the pharmacological inhibition of CD73 enzymatic activity could be considered as a means to potentiate the anti-cancer effects of NAMPT inhibitors." (PMID 26658104, 2016). "Furthermore, NAMPT inhibition using a siRNA in the presence of GMX1778, another NAMPT inhibitor, increased apoptosis of different cancer cells." (PMID 27462772, 2016). "Notably, opposite to cancer cells, activated immune cells, along with many other types of healthy cells, such as hematopoietic stem cells, appear unaffected by NAMPT inhibitors, and consistently, agents such as FK866 or CHS-828 are well tolerated in patients." (PMID 26542945, 2015). "High NAMPT levels, whose activity appears to be also important in the differentiation of myeloid cells, were shown to be required to support cancer cell growth, survival and epithelial-mesenchymal transition (EMT) transition, and have been reported in different types of tumors." (PMID 26542945, 2015).
cancer (continued). "The downregulation of NAMPT promotes apoptosis in cancer cells and attenuates tumor growth." (PMID 25946974, 2015). "NAMPT protein is a secreted plasma biomarker in inflammation and in cancer." (PMID 25146220, 2014). "The impact of the NAMPT inhibition on lipogenesis in cancer cell lines was previously reported." (PMID 25486521, 2014). "The profound effects of NAMPT inhibition on cancer cell metabolism could serve as a basis for further understanding of the physiological role of NAMPT in cancer cell metabolism." (PMID 25486521, 2014). "Preclinical research has demonstrated that pharmacological targeting of NAMPT may be an effective strategy against certain cancers, and while several early-phase clinical trials testing NAMPT inhibitors in refractory cancers have been completed, drug resistance is a concern." (PMID 40342733, 2025). "Targeting NAMPT, which is selectively activated by oncogenic kinases to which malignant cells become “addicted,” may represent a novel therapeutic approach to cancer, either as an alternative or, more likely, as a complementary strategy to direct inhibition of the kinase enzymatic domain." (PMID 40775221, 2025). "Thus, the therapies targeting NAD+ metabolism, such as PARP and NAMPT inhibitors, could enhance cancer cell death by blocking NAD+ dependency." (PMID 40076592, 2025). "Notably, cancer cells expressing high levels of NAPRT are resistant to NAMPT inhibitors." (PMID 37259338, 2023). "Thus, NAMPT and CtBP inhibitors exert highly cooperative cancer-selective antiproliferative effects in certain PDAC cell lines, but not in untransformed pancreatic ductal cells or PDAC cells where alternative NAD synthesis pathways may be active." (PMID 37707363, 2023). "NAMPT expression may considerably alter how cancer cells may react to different treatments." (PMID 37583931, 2023). "However, PH-dependent cancers with upregulated NAPRT expression are resistant to NAMPT inhibitors." (PMID 38116009, 2023). "In addition, a connection between NAMPT and mTOR activation has been shown in various cancers." (PMID 38116009, 2023). "Consequently, it becomes imperative to identify effective NAMPT inhibitors that selectively target NAPRT-deficient cancers, both as monotherapy and in combination with standard chemotherapy, to overcome the challenges posed by potentially malignant tumors." (PMID 37771778, 2023). "Importantly, the abnormal NAMPT expression level in various types of cancers has been detected." (PMID 35565188, 2022). "Altogether, the data suggest that whenever NAM is available, any NA-producing microorganisms such as various bacteria species (for instance gut microbiota), may strongly reduce the efficacy of NAMPT inhibitors by activating NAD+ production through the Preiss-Handler pathway in cancer cells." (PMID 35396381, 2022). "Thus, NAMPT has been proposed as a suitable target for cancer therapy." (PMID 36078035, 2022). "In particular, NAMPT-mediated signaling pathways play a pivotal role in modulating key processes involved in cancer progression, including angiogenesis, cancer cell metastasis, proliferation, cancer stemness, and chemoresistance to anticancer drugs, which are summarized and shown." (PMID 35565188, 2022). "In addition to the differences in experimental procedures used by research groups, NAMPT-mediated biological effects might be partly determined by interactive cofactors and receptors that are still unknown for specific cancer types." (PMID 35565188, 2022). "Moreover, a combination between NAMPT inhibitors and selective inhibitors of oncogenic signaling driving cancer progression could be therapeutically exploited as suggested." (PMID 34421911, 2021).
cancer (continued). "Thus, through its control of NAD biosynthesis, NAMPT has a crucial role in cancer cell metabolism." (PMID 33912035, 2021). "Additionally, it was reportedthat NAMPT is necessary for de novo lipid biosynthesisin cancer." (PMID 32779442, 2020). "Indeed, NAMPT inhibitors suppress cancer cell proliferation by inhibiting glycolysis." (PMID 32295316, 2020). "Moreover, NAMPT is also a key factor inducing cancer stem pathway effectors in colon cancer tumors." (PMID 31119097, 2019). "Consequently, it was hypothesized that down-regulated miR-381 in cancer cells might be involved in NAMPT up-regulation." (PMID 31611752, 2019). "Thus, NAMPT is an attractive metabolic target for cancer treatment." (PMID 30856230, 2019). "Thus, if we could downregulate NAMPT expression or function in patients with NAMPT+ PDAs, we could potentially delay cancer progression and prolong survival similar to those with NAMPT- PDAs." (PMID 30856230, 2019). "LDHA expression and enzymatic activity were both increased in MDA RES, as well as in CEM RES, suggesting that LDHA activity may be not only a common mechanism of acquired resistance to NAMPT inhibition but also a new possible vulnerability of FK866-resistant cancer cells." (PMID 29541451, 2018). "Thus, targeting LDHA together with NAMPT may offer novel opportunities for selective killing of cancer cells, particularly in cancer types that are addicted to aerobic glycolysis for survival." (PMID 29541451, 2018). "Moreover, we observed higher NAMPT expression in cancers with lymph node involvement, suggesting that NAMPT might be a molecular marker of poor prognosis." (PMID 25946974, 2015). "Furthermore, it has been proposed that the therapeutic index for NAMPT inhibitors can be increased in patients whose cancers lack NAPRT1, an essential enzyme in an alternative NAD synthesis pathway that utilizes nicotinic acid (NA, naicin, vitamin B3) as a starting point." (PMID 25285661, 2014). "However, how modulating the NAMPT activity in cancer cells affects cellular metabolism, outside of energy metabolism as previously reported, remains unknown." (PMID 25486521, 2014). "Nicotinamide phosphoribosyltransferase (NAMPT) is a rate-limiting enzyme widely present in tumor cells, has the potential to be targeted by inhibitors for cancer therapy." (PMID 41355972, 2026). "Nicotinamide phosphoribosyltransferase (NAMPT) is the rate-limiting enzyme in the NAD+ salvage pathway and a promising therapeutic target in cancer." (PMID 41608637, 2026). "To confirm that NAMPT is a functional target of PF403, we knocked down the NAMPT gene in the U87 cancer cell line with three shRNA interference sequences by lentiviral infection." (PMID 40486861, 2025). "Another first-generation NAMPT inhibitor, GMX1777, also displayed an improved therapeutic index against cancer cells with low NAPRT expression in vivo, when administered at high doses with nicotinic acid rescue." (PMID 40526635, 2025). "Upregulated NAMPT in the scavenger pathway is a central contributor to the NAD+ pool, which can supply cancer cells with the ability to meet increased energy needs." (PMID 40722609, 2025). "NAMPT catalyzes the rate-limiting step in the NAD+ salvage pathway of mammalian cells and is overexpressed in numerous types of cancers." (PMID 40342733, 2025). "In addition, many non-recurrent mutations in NAMPT have also been reported in a variety of cancers." (PMID 40342733, 2025). "In terms of cellular crosstalk, SPP1+ TAMs express SPP1 and nicotinamide phosphoribosyl transferase (NAMPT) to interact with the stroma and cancer cells." (PMID 41341850, 2025). "It has also been shown that the expression of nicotinamide phosphoribosyltransferase (NAMPT), an essential enzyme for NAD+ synthesis, is increased in the most aggressive and invasive cancers and in tumor metastases." (PMID 39982908, 2025). "For example, YAPoff cancers are highly sensitive to inhibitors of BCL2-family proteins, NAMPT, XPO1, Aurora kinases, and HDACs." (PMID 40440076, 2025).
cancer (continued). "Cancer cells undergoing EMT frequently exhibit alterations in NAD biosynthesis pathways, particularly involving the enzymes NAMPT and NAPRT." (PMID 40282553, 2025). "By inhibiting NAMPT, intracellular NAD levels are depleted, leading to impaired energy metabolism and subsequent cancer cell death." (PMID 40282553, 2025). "The adipokine visfatin, also known as nicotinamide phosphoribosyltransferase (NAMPT), has garnered attention for its potential role in cancer biology." (PMID 41036084, 2025). "NAMPT and SIRT1 are overexpressed in several malignant tumor types, including colorectal, ovarian, breast, gastric, thyroid, and prostate cancers, as well as numerous malignant lymphomas, due to the increased requirement for energy metabolism." (PMID 40085284, 2025). "Inhibitors of nicotinamide phosphoribosyltransferase (NAMPT), such as FK866, interfere with nicotinamide adenine dinucleotide (NAD+) biosynthesis and suppress therapy-induced senescent cancer stem-like cells." (PMID 40867884, 2025). "NAMPT has been reported to be the rate-limiting enzyme of NAD + biosynthesis and is overexpressed in several types of cancer cells to satisfy the continuous requirement for rapid proliferation." (PMID 40486861, 2025). "Among the identified NAMPT inhibitors, the prototypical compound FK866 and CHS-828, with its prodrug GMX1777, have been evaluated in early-phase clinical trials involving cancer patients." (PMID 39272943, 2024). "To evaluate the role of MAFG in mediating TWEAK-driven NAMPT expression, we found a significant positive correlation between MAFG and NAMPT expression in the TCGA BRCA and Pan-cancer dataset." (PMID 38965263, 2024). "Intriguingly, alterations in NAMPT levels are associated with metabolic disorders and cancer, while FK866 (a highly specific NAMPT inhibitor that abolishes NAD+ circadian oscillations and SIRT1 cycle activity) can induce apoptosis in human cancer cells." (PMID 39012661, 2024). "Amongst the identified NAMPT inhibitors, the prototypical compound FK866 (also known as (E)-Daporinad), CHS-828, and its prodrug GMX1777 were evaluated in cancer patients in early-phase clinical trials." (PMID 38396769, 2024). "Several studies have shown that NAMPT and NAD+ are frequently upregulated in several human malignancies and play key roles in the development, progression, and recurrence of cancer." (PMID 38448544, 2024). "NAMPT inhibitors, such as FK866, reduce NAD levels and inhibit cancer cell proliferation by interfering with energy production pathways." (PMID 38225236, 2024). "Therefore, NAMPT inhibitors may be ineffective for NAMPT-independent cancers in the clinic." (PMID 38424218, 2024). "Genes such as PARP1, NAMPT, AIMP2, MCL1, and TOMM20 exhibited widespread amplifications of CNVs in multiple cancers, while genes like RNF146, GPX4, ESR1, CUL4A, and PTEN showed widespread deletions." (PMID 38499384, 2024). "VAD is a toxic metabolite that blocks the activities of NAMPT, NMNAT, and other NAD+-dependent enzymes, leading to a catastrophic NAD+ depletion, metabolic impairment, and cancer cell lethality." (PMID 38396769, 2024). "Although KPT-9274 was previously shown to inhibit both PAK4 and NAMPT, we had assumed that most PAK4 inhibitors block cancer cell growth primarily due to the inhibition of PAK4." (PMID 39337621, 2024). "NAMPT is an enzyme that plays a key role in the NAD+ biosynthesis pathway, and its inhibitors have shown potential in cancer therapy." (PMID 39513038, 2024). "It is worth mentioning that the inhibition of NAPRT decreases OXPHOS in cancer cells that overexpress NAPRT and makes them more sensitive to NAMPT inhibitors (NAMPTi)." (PMID 38116009, 2023). "Reciprocally, activated myeloid cells regulate the activation of MFAP5 + fibroblasts in a positive feedback mode by secreting cancer-promoting ligands that contain EGF superfamily proteins and NAMPT." (PMID 37344903, 2023).
cancer (continued). "Given the importance of the NAD+ supply in cancer cell survival and the SL relationship between two critical enzymes in NAD+ metabolism, NAMPT and NAPRT, we discovered a novel NAMPT inhibitor with improved biomarker selectivity." (PMID 37771778, 2023). "The viability, invasion, and migration of cancer cells are reduced by the KPT-9274, which is a hybrid inhibitor of NAMPT and serine/threonine–p21-activated kinase 4 (PAK4)." (PMID 37175631, 2023). "Concordantly, NAMPT inhibitors, such as FK866, have been tested as a novel cancer therapy and showed reduced tumor burden in preclinical studies, leading to several clinical trials (NCT00432107, NCT00431912)." (PMID 36900204, 2023). "Cancers are classified into two categories depending on the predominant pathway of NAD+ synthesis: NAPRT- and NAMPT-dependent cancer." (PMID 37175631, 2023). "According to the upregulated NAD+ synthesis pathway, cancer cells can be divided into PH-amplified tumors, many of which show NAPRT amplification, and salvage-dependent tumors, which are characterized by NAMPT enhancer remodeling." (PMID 38116009, 2023). "On the basis of this, NAMPT was identified as a target of intervention and FK866, a drug limiting cancer development in preclinical studies." (PMID 37414778, 2023). "To date, such molecular pathways are known that regulate the expression and activity of NAMPT in cancers, such as c-MYC/NAMPT/SIRT1, HMGA1/NAMPT/NAD+, FOXO1/NAMPT, NAMPT/miRNA, SIRT6/SIRT1/NAMPT, C/EBPβ/NAMPT." (PMID 37175631, 2023). "The major enzyme in the nicotinamide-adenine dinucleotide (NAD+)-mediated pathways, nicotinamide phosphoribosyltransferase (NAMPT), is essential for cancer cell survival and metastasis." (PMID 36899911, 2023). "Similar to the potential cross-talk between mesothelial cells and cancer cells, we identified possible interactions between LA-TAMs/mesothelial cells by SPP1, RETN, LGALS9, NAMPT, and HBEGF secretion." (PMID 37649596, 2023). "Several studies reported that anti-tumor drugs in combination with inhibition of NAMPT, a rate-limiting enzyme in the NAD salvage pathway, can synergistically inhibit cancer cell proliferation." (PMID 36986177, 2023). "Consequently, employing NAMPT inhibitors could be an attractive option for cancer therapy." (PMID 37046703, 2023). "NAMPT has been described to enhance tumor aggressiveness by modulating the EMT and supporting cancer cell stemness." (PMID 38116009, 2023). "Pharmacological inhibition of nicotinamide phosphoribosyltransferase (NAMPT), an enzyme essential for NAD+ biosynthesis has shown promising results in cancer therapy by repressing glycolytic phenotype." (PMID 37298093, 2023). "Our studies on both MCF7 and 231 cells further highlight the importance of NAMPT in maintaining cellular NAD+ levels and in the ability of cancer cells to maintain an energy balance to avoid cancer therapy cytotoxicity." (PMID 37583931, 2023). "NAMPT is the major rate-limiting enzyme in NAD+ salvage biosynthesis, which can promote cancer cell proliferation, migration, stemness, and metastasis." (PMID 37491379, 2023). "Nicotinamide phosphoribosyltransferase (NAMPT), a key enzyme for NAD synthesis, has been proposed as a potential target for cancer therapy." (PMID 38092728, 2023). "Visfatin (NAMPT) is the rate-limiting enzyme in NAD+ biosynthesis, and its expression is excessive in many cancers." (PMID 37190027, 2023). "The high-mobility group A (HMGA1) protein participates in the regulation of NAMPT expression through NAD+-mediated enhancement of the NF-κB activity, contributing to the inflammatory environment and stimulating cancer progression." (PMID 37175631, 2023). "Bulk-RNAseq and scRNAseq revealed that, in addition to NAMPT inhibition, FK866 regulates tumor metastasis, cell migration, invasion, DNA repair machinery, redox homeostasis, autophagy, as well as cancer stemness–related genes, HES1 and CD44." (PMID 36497496, 2022).